SLPI (secretory leukocyte peptidase inhibitor)
Diseases named in the same sentence as SLPI in open-access papers (continued):
Sharing a sentence is not in itself a finding about the gene and the disease.
tumor (continued). "Elevated SLPI was associated with lower metastasis whereas absent/weak abundance of SLPI was associated with increased tumor burden of the neck." (PMID 23467841, 2013). "Moreover, repression of the MMP inhibitor TIMP2 and serine protease inhibitor SLPI can enhance tumor invasion and has been reported in several cancers." (PMID 23024765, 2012). "However, in several malignancies, SLPI paradoxically plays a tumor-promoting role." (PMID 41557653, 2026). "In addition, the tumor-promoting functions of SLPI demonstrated in this study suggest that SLPI may represent a candidate therapeutic target." (PMID 41557653, 2026). "SLPI could also expedite tumor progression and facilitate tumor metastasis." (PMID 39170693, 2024). "Also, the overexpression of the SLPI gene from mammary tumor cells reduced tumor development and enhanced the survival rate among mice and was thought to exert pro-apoptotic functions and suppress tumor cell growth." (PMID 36595102, 2023). "In addition, cleavage of caspase-9/-3 and PARP1 was increased in PI3/SLPI-deficient cells upon TRAIL treatment, substantiating the tumor-protective role of these two peptidase inhibitors through regulation of both intrinsic and extrinsic apoptosis pathways downstream of TSPO." (PMID 37158962, 2023). "In summary, our findings highlight that SLPI could serve as a potential prognostic biomarker and putative tumor suppressor by enhancing ER stress-induced apoptosis in HCC cells mediated by MAPK signaling pathways, which provides new insights into promising therapeutic targets for HCC treatment." (PMID 34975323, 2022). "Hence, our data indicated that SLPI was a tumor suppressor and a pivotal biomarker for HCC therapy." (PMID 34975323, 2022). "Thus, we studied different steps in the progression of CRC in this cohort and our previous cohort and we show that SLPI expression may relate to different biological processes or have a different consequence for the tumor." (PMID 35842496, 2022). "However, SLPI has multiple diverse functions and may act differently in various processes related to tumor growth and metastasis." (PMID 35842496, 2022). "Moreover, the expression levels of SLPI were correlated with tumor growth and invasion capacities." (PMID 34975323, 2022). "From our perspective, the contradictory role of SLPI in tumor progression might be due to the different tumor origins and pathological types and the fact that SLPI regulates distinct targets in different cancers may also account for the opposing effect of SLPI on tumor progression." (PMID 31462893, 2019). "However, in some cases overexpression of SLPI at the primary tumor site repressed metastases." (PMID 29312532, 2017). "SLPI, WFDC2, WFIKKN2, and WFDC1 consistently showed low expression across tumor types, whereas WFDC5, WFDC3, and WFIKKN1 displayed heterogeneous expression profiles." (PMID 40350979, 2025). "Statistical analysis showed significant tumor-specific upregulation of WFDC1, WFDC2, WFDC3, SLPI, PI3, and ANOS1 (P < 0.0001), while WFIKKN1 was notably downregulated in neoplastic tissues (P < 0.0001)." (PMID 40350979, 2025). "Subsequent univariate Cox and LASSO regression analyses narrowed the selection to five key genes—GGT6, HAO2, SLPI, MELK, and EIF4A1—whose expression patterns correlated strongly with tumor grade, clinical stage, and metastatic status." (PMID 40709174, 2025). "As an emerging tumor marker, HE4 has attracted much research attention since its discovery because it is a member of the WFDC family homologous to SLPI and Elafin proteins." (PMID 38742362, 2024). "To reveal the intra-tumor heterogeneity of malignant epithelial cells, we categorized the obtained cells into four subtypes: C0 TRPM4+ malignant cells, C1 SLPI+ malignant cells, C2 MIR205HG+ malignant cells, and C3 NEFH+ malignant cells." (PMID 39759507, 2024).
tumor (continued). "The differential mRNA expression analysis of genes included in the AVENIO surveillance panel demonstrated that MET, EGFR, SLPI, and TNFRSF21 had the highest difference in log2(TPM + 1) between NSCLC tumours and PBMCs." (PMID 36825535, 2023). "More importantly, it was found that exogenous SLPI reserves Akt expression in E6-expressing HNSCC cells, and consequently it induces apoptosis and mitigates tumor invasiveness." (PMID 37237486, 2023). "Together, these results confirmed that the aberrant expression of SLPI can suppress the expression of PUMA, block its pro-apoptotic functions, and subsequently promote tumor growth." (PMID 36595102, 2023). "To further evaluate the anti-tumor effect of SLPI in vivo, we performed a xenograft formation experiment in BALB/C nude mice by using both SLPI-overexpressed SK-Hep-1 and SLPI-underexpressing BEL 7402 cells." (PMID 34975323, 2022). "Macrophages altered by tumor CCL5 expression and EVs have increased expression of several genes known to drive invasion and metastasis, including OPN, SLPI, HGF, and NRG3." (PMID 34298673, 2021). "SLPI also plays an important role in the regulation of cell cycle progression by promoting the expression of cyclin D1 and IGFBP-3 in tumor cells." (PMID 32742768, 2020). "Therefore, SLPI may be a potential tumor marker to predict the prognosis." (PMID 33381555, 2020). "The HE4 tumor-promoting activities appear similar to those found in other WAP proteins, namely elafin and SLPI." (PMID 23502467, 2013). "Indeed, this study revealed that three serpins secreted by cells in the tumor microenvironment (TME), including A1AT, SERPINB1, and SLPI, can antagonize ELANE’s anti-tumor capability in a dose-dependent manner." (PMID 34599140, 2021). "Interestingly, CCL7, CCL19, CXCL7, NRG3, SLPI, OPN, and HGF in macrophages are upregulated in response to increased tumor CCL5 expression." (PMID 34298673, 2021). "Upregulation of SLPI is associated with tumor grade and TNM stage (tumor, node, metastasis), but not with patients’ sex or age." (PMID 32742768, 2020). "Besides that, it has been reported that SLPI was up-regulated in colon cancer tissues when comparing to normal mucosa, and correlated with differentiation grade, TNM (tumor, node, metastasis) stages, lymph node metastasis and distant metastasis." (PMID 32742768, 2020). "Overall, it came to the conclusion that SLPI could interfere with multiple pathways through which E6 oncogene performed its tumor promoter role in HNSCC, suggesting the potential therapeutic effect of SLPI on E6 positive HNSCC." (PMID 31462893, 2019). "We further demonstrated that this effect is not restricted to the tumor process and that SLPI and CTGF expression is directly regulated by IGF1R." (PMID 27179633, 2016). "Overexpression of SLPI is correlated with tumor grade and TNM stage, but not with patient age or sex." (PMID 25441765, 2014). "Additionally, several tumor related genes, including Maspin, WFDC1, SLPI, S100P, and PDGFRB, were shown to be differentially expressed in MGC803 cells in response to latexin expression." (PMID 21466706, 2011). "SLPI regulates the proliferation, migration, and invasion capabilities of HCC cells via apoptosis through the mitogen-activated protein kinase (MAPK) signaling pathway, indicating its potential as both a tumor suppressor and a biomarker for HCC prognosis and treatment." (PMID 40005897, 2025). "In localized PC patients, who were not androgen‐ deprived, SLPI expression and AR expression were positively correlated and may have affected tumor growth; nevertheless, further research is needed." (PMID 36812122, 2023). "SLPI may also promote vascular invasion via induction of MMP-2 and MMP-9 production by tumor cells." (PMID 35842496, 2022). "Alternatively, irrespective of whether there is a difference in the tumor cells expressing SLPI, SLPI may exert opposing functions during the course of disease." (PMID 35842496, 2022).
tumor (continued). "In our previous study, we have confirmed that SLPI is highly expressed in HEP-2 cells (now denoted as HeLa contaminant by American Type Culture Collection), and recombinant adenovirus armed with revCASP3 under the control of SLPI promoter has specific tumor targeting." (PMID 32745124, 2020). "In our previous study, we identified that SLPI abundance in HNSCC tissues is much lower than that in normal tissues and that SLPI could act as a tumor suppressor by inhibiting proliferation and promoting apoptosis of HNSCC cells, suggesting a tumor suppressive role of SLPI in HNSCC." (PMID 31462893, 2019). "Finally, we identified a compound in a small-molecule library that inhibited SLPI at non-toxic concentrations and pharmacologically decreased both primary 4T1 tumor growth and lung metastasis." (PMID 29312532, 2017). "Thus our results with the mammalian two-hybrid system indicate that SLPI protein physically interacted with Rb tumor suppressor but not FoxM1, and also confirmed the known interaction of Rb and FoxM1 proteins." (PMID 29312532, 2017). "In this context, SLPI overexpression was associated with increased MMP-9 activity, upregulation of VEGFA and VE-cadherin, and suppression of N-cadherin—molecular features that are characteristic of VM-competent tumor cells rather than endothelial-dependent angiogenesis." (PMID 41557653, 2026). "Interestingly, researchers found that genetically modified tumor cells with SLPI overexpressing did not exhibit tumorigenesis in immunocompetent mice and may act as a vaccine that partially restrains tumor growth and stimulate the adaptive immune response." (PMID 36588538, 2022). "The data presented here demonstrate that high SLPI expression is correlated with reduced prevalence of HPV infection in the investigated tumor specimens of HNSCC, while the HPV-positive cases predominate in the group of absent to low SLPI expression." (PMID 23467841, 2013).
cancer (63 papers, 2010 to 2026). A tumor composed of atypical neoplastic, often pleomorphic cells that invade other tissues. "Among the molecules associated with inflammation and cancer progression, Secretory Leukocyte Protease Inhibitor (SLPI) has garnered attention due to its multifunctional role." (PMID 41557653, 2026). "Recent studies have demonstrated that SLPI expression enhances the metastatic capacity of malignant cells and is associated with poor prognosis in several types of cancer." (PMID 40900789, 2025). "In cancer, SLPI has been shown to be associated with cell proliferation, apoptosis, invasion and metastasis." (PMID 38969699, 2024). "Its expression has been reported as context‐dependent; however, SLPI overexpression is commonly associated with high‐risk aggressive cancer from various organs." (PMID 36812122, 2023). "Recent investigations have demonstrated that aberrant expression of SLPI was strictly linked to various human cancers development like lung, ovarian, cervix, neck, and pancreas cancers." (PMID 36595102, 2023). "Mechanistically, blockage of cancer cell growth and metastasis after SLPI knockdown was associated with down-regulation of AKT signaling." (PMID 32742768, 2020). "Conceivably, SLPI seemingly accelerates the ability of cancer cells to migrate by upregulating genes associated with the organization of the actin cytoskeleton, including WASF1 and WASF3." (PMID 33016205, 2020). "Since it has been suggested that the inhibition of multiple signalings is necessary for HPV-associated cancers, we supposed that SLPI may serve as a candidate therapy agent." (PMID 31462893, 2019). "SLPI has been implicated in the progression and metastasis of certain cancers." (PMID 29312532, 2017). "This study aimed to elucidate the mechanism underlying SLPI-induced enhancement of the malignant phenotype by characterizing the morphology of both the actin filament and cell adhesion structures in SLPI-expressing cancer cells and to identify the molecules associated with the process." (PMID 33016205, 2020). "This diverse behavior underscores that SLPI function in cancer is tissue-specific and dependent on the functional or pathological state." (PMID 41681959, 2026). "These oncogenic effects are consistent with SLPI-mediated tumorigenic processes reported in other cancers." (PMID 41557653, 2026). "Secretory leukocyte peptidase inhibitor (SLPI) has been reported to promote the tumorigenic and metastatic potential of cancer cells." (PMID 41035689, 2025). "High SLPI expression was detected in 10 cancer types, and low SLPI expression was detected in 10 cancer types." (PMID 40196737, 2025). "A strong correlation exists between aberrant SLPI expression and the development of various human cancers, including lung, ovarian, cervical, neck, and pancreatic tumors." (PMID 40005897, 2025). "Next, we evaluated the TCGA database to determine the relationship between overall survival and SLPI expression in pan-cancer, which concluded that patients with high SLPI expression had poor survival prognosis." (PMID 37312410, 2023). "Meanwhile, the IC50 concentration of cisplatin for cancer cells reduced dramatically from 5.8 μg/mL in control cells to 2.27 μg/mL in SLPI siRNA-transfected cells, demonstrating that siSLPI enhances the CRC chemosensitivity to Cisplatin treatment." (PMID 36595102, 2023). "The IDEGs (SLPI, IAPP, NPY, ISG15, PLA2G2A, and HLA-DMB) in the predictive PCa risk model constructed in the present study play an important regulatory role in cancer." (PMID 36774376, 2023). "Secretory leukocyte protease inhibitor (SLPI) has been reported to function as a regulatory factor in several cancers." (PMID 34975323, 2022). "Recently, increased SLPI expression was found in various types of carcinomas and was suggested to increase their metastatic potential." (PMID 35842496, 2022). "Alternatively, SLPI plays a role in cancer cell malignancy and is upregulated in various types of cancer cells." (PMID 33016205, 2020).
cancer (continued). "Recent studies showed that SLPI is also upregulated in several human cancers including lung, cervix, ovarian, pancreas and head/neck cancers, and is associated with cancer progression, metastasis and invasion." (PMID 32742768, 2020). "SLPI has been reported to be upregulated in a variety of cancers and plays important role in metastasis of cancer cells." (PMID 32742768, 2020). "By contrast to other types of cancers, in which higher SLPI expression levels correlated with worse clinical outcome, SLPI was found in decreased levels in both oral premalignant lesion tissue and OSCC lesion tissues compared to healthy normal tissue." (PMID 31890650, 2019). "SLPI has also been reported to play a role in cell proliferation, cancer progression, metastasis, and invasion." (PMID 28255192, 2017). "SERPINE2 and SLPI have also been postulated as new molecular targets in the therapy of certain cancers." (PMID 28255192, 2017). "A recent study showed that SERPINE2 and SLPI are produced in cancer tissues and are overexpressed under tumorigenic conditions." (PMID 28255192, 2017). "Most notably, HE4 together with other proteins of this family, elafin, PS20, and SLPI, have been identified as potential molecular biomarkers for cancer." (PMID 27589683, 2016). "Recent study showed that SLPI expression in relation to cancer progression, metastasis and invasion." (PMID 25954138, 2015). "Such a protective role of SLPI has previously been described, and has been assigned to the theory that SLPI affects the invasive activity of cancer cells by inhibiting enzymes promoting cancer invasion and progression." (PMID 23467841, 2013). "In contrast, secretory leukocyte protease inhibitor (SLPI) which is also a protease inhibitor but functions to enhance cancer invasion was downregulated by latexin expression to less than one half of control level." (PMID 21466706, 2011). "Although angiogenesis is a hallmark of cancer progression, our findings suggest that SLPI does not promote classical angiogenesis in endothelial cells." (PMID 41557653, 2026). "Importantly, the degree of SLPI-driven CCG was greater in CCA cells with high metastatic potential than in SLPI-overexpressing cholangiocytes, suggesting a dose-dependent role of SLPI in promoting cancer aggressiveness." (PMID 41557653, 2026). "Interestingly, recent studies have identified SLPI as an oncogenic factor that is upregulated in several cancer types including lung, ovarian, and pancreatic cancers." (PMID 41557653, 2026). "Given the strong link between chronic inflammation and CCA, and SLPI’s established involvement in both inflammatory regulation and cancer progression, we hypothesized that SLPI may act as a key regulator of cholangiocarcinogenesis." (PMID 41557653, 2026). "Increased expression of SLPI was also found in multiple human cancer types." (PMID 37312410, 2023). "Recent studies have identified many genes that play pivotal roles in various cancers; the secretory leukocyte protease inhibitor (SLPI), mainly generated and released by epithelial and inflammatory cells, has been widely reported as an emerging anti-inflammatory." (PMID 36595102, 2023). "The mechanisms of SLPI in cancer cell proliferation and metastasis have been previously reported." (PMID 36812122, 2023). "Conversely, SLPI showed hypomethylation in nearly all cancers, with the exception of PRAD." (PMID 37604837, 2023). "SLPI promotes metastasis in some cancer types, while long-term administration of serine protease inhibitor may develop metabolic side effects and spontaneous bleeding in hemophiliac patients." (PMID 36061560, 2022). "SLPI plays a role in focal adhesion of cancer cells to the surrounding environment." (PMID 33837198, 2021). "SLPI is overexpressed in many types of cancer, such as ovarian cancer, breast cancer, and HNSCCs." (PMID 32745124, 2020).